PDK1 (pyruvate dehydrogenase kinase 1)
Diseases named in the same sentence as PDK1 in open-access papers (continued):
Sharing a sentence is not in itself a finding about the gene and the disease.
tumor (continued). "Previous reports have well documented the AKT-independent tumor-promoting activities of PDK1." (PMID 37531320, 2023). "PDK1 clearly partially mediates MAPK4 tumor-promoting activity." (PMID 37531320, 2023). "In tumor cells, upregulated PDK1–4 can inhibit PDH activity and support aerobic glycolysis." (PMID 37818192, 2023). "In addition, the PDK1 inhibitor BX795 mediates glycolysis in tumor cells by downregulating the PDK1/CD47/AKT signaling pathway." (PMID 37783914, 2023). "The increased PDH activity in Hepa-c4 cells could be due to the lower expression of PDK-1 (an inhibitor of PDH) observed in Hepa-c4 cells grown as tumours." (PMID 36429023, 2022). "Intriguingly, a study reported that light at night activated IGF-1 R/PDK1 signaling and accelerated tumor growth of MCF-7 cells in nude rats, which could be inhibited by PDK1 knockdown." (PMID 35159078, 2022). "In particular, PDK1 increases significantly in breast CSCs under hypoxia, and the inhibition of PDK1 may reduce the formation of mammospheres and the ability of tumor growth in vivo." (PMID 36474273, 2022). "Western blotting of tumour tissue lysates revealed that PDK1 protein levels were significantly decreased after the knockdown of FOXM1, while the protein levels of PDK1 were restored by upregulating PDK1 expression, suggesting that the knockdown of FOXM1 can regulate the expression of PDK1 in vivo." (PMID 35656815, 2022). "The tumor progression can effectively slow down by downregulating tumor immune escape via PDK1." (PMID 36245844, 2022). "Pyruvate dehydrogenase kinase 1 (PDK1), which could inactivate PDH and is an independent risk factor for NSCLC, is highly expressed in tumor tissues of NSCLC patients, and its overexpression promotes the proliferation and metastasis of NSCLC." (PMID 36532721, 2022). "All in all, our findings indicate that circKIF4A may influence NKTL tumor growth through modulating PDK1 and BCL11A expression by functioning as a ceRNA for miR-1231." (PMID 36230873, 2022). "The roles of miR-148a/PDK1 in tumor growth were investigated in vivo." (PMID 35892859, 2022). "The inhibition of PDK1 expression level can repress tumor progression and metastasis." (PMID 34868313, 2021). "In order to test whether PDK1 silencing may also potentiate the effects of TKI treatment on tumor growth, we investigated the expression levels of several key proteins of proliferation and apoptosis." (PMID 34439291, 2021). "Mechanistically, Chibby suppresses Wnt/β-catenin/PDK1/Lin28/Let-7g to control tumor proliferation." (PMID 35008539, 2021). "Also, SIPA1 knockdown decreased the expressions of EPAS1, glycolysis-related products and PDK1 in tumor tissues at mRNA and protein levels." (PMID 35096814, 2021). "Thus, modulation of the Lin28/let-7 axis regulates tumor glycolytic metabolism through direct or indirect regulation of PDK1 activity, which directs glucose influx into aerobic glycolysis." (PMID 34572067, 2021). "Apoptosis and cell cycle experiments results revealed that PDK1 could affect the proliferation of tumor cells in S phase, in other words, replication phase." (PMID 33403023, 2021). "Moreover, our findings hint at an impact of PDK1 silencing on angiogenesis but tumor model-specific differences appeared to be prominent." (PMID 33562444, 2021). "From the diagrams, tumor cells exhibited cytoplasmic immune reaction of PDK1." (PMID 33403023, 2021). "The results demonstrated that downregulation of the ARNT/PDK1 axis and the increase in ROS may confer tumor cells with the ability to metastasis." (PMID 33446631, 2021). "Interestingly, PDK1 is reported to be enriched in ALDH+ CSCs, and the depletion of PDK1 diminishes the sphere-forming ability and tumor growth by abrogating ALDH+ CSCs." (PMID 34572067, 2021).
tumor (continued). "Taken together, our data indicate that in different tissues or cellular compartmental conditions, SPOP might play different roles as tumor suppressor or oncogene in manipulating AKT kinase by degrading distinct substrates such as PDK1 or PTEN, respectively." (PMID 34353330, 2021). "Indeed, we found that treatment of tumor cells with NAC, CCCP and rotenone inhibited ARNT or PDK1 deficiency-induced tumor migration and invasion through the reduction of epithelial mesenchymal transition (EMT)." (PMID 33446631, 2021). "The high expression of PDK isoenzymes in tumor tissues is closely related to abnormal glycolysis in tumors, especially PDK1, which is the only kinase that can phosphorylate the three phosphorylation sites of E1 and is related to the prognosis of cancer patients." (PMID 33739396, 2021). "In addition, we found that PDK1 downregulation, as well as ARNT knockdown caused a switch in glucose consumption to initiate tumor metastasis." (PMID 33446631, 2021). "In univariate analysis at UTUC, tumor location, multi-focal tumors, T stage, lymph node metastases, vascular invasion, high tumor grade, peri-neural invasion, PDK1 overexpression, and PDK3 overexpression were all found to be significantly associated with poor prognostic factors for MFS and DSS." (PMID 34589439, 2021). "Here, we tested whether knocking down PDK1 by short hairpin RNA may enhance the effects of TKIs on mitochondrial oxidative phosphorylation and improve tumor response to these targeted agents in NSCLC." (PMID 34439291, 2021). "Another possible mechanism of EOC chemoresistance may be related to PDK1, which is involved in tumor growth and progression, cancer cell invasion and dissemination, and chemoresistance." (PMID 34944877, 2021). "PDK1 knockdown resulted in significant reduction of tumor growth (left)." (PMID 32071289, 2020). "Therefore, restoration of mitochondrial oxidative phosphorylation by PDK1 inhibition becomes a potential new therapeutic target for tumor treatment 31-33." (PMID 31949499, 2020). "The knockdown of PDK1 could also increase mitochondrial oxygen consumption and inhibit tumor proliferation by activating apoptosis." (PMID 33318678, 2020). "We also highlight the tumor suppressor miR-375 that decreases PDK1 activity in PI3K/Akt signaling." (PMID 32708088, 2020). "Similarly to PDK1, PDK3 is induced by HIF-1α, and higher expression is associated with higher tumor stage in many cancers." (PMID 33384955, 2020). "In vivo, PDK1 knockdown attenuated tumor dissemination in nude mice." (PMID 32071289, 2020). "PDK1 depletion additionally hindered tumor growth and dissemination in nude mice in vivo." (PMID 32071289, 2020). "The anti-tumor effect of HsA was suppressed in PDK1 silencing DLD-1 cells." (PMID 33318678, 2020). "This suggests that exploring the role of PDK1 might explain the role of mitochondria in tumor cells." (PMID 31949499, 2020). "Constitutive activation of PI3K/PDK-1/Akt signalling pathway could promote cancer cell survival, tumor growth, and resistance to the anticancer drug in many human cancer cells." (PMID 30717410, 2019). "BX-912, a PDK1 inhibitor, has been shown to suppress tumor growth in vitro and in vivo." (PMID 30779739, 2019). "In addition, previous studies have shown that OSM can promote glycolytic mechanisms in human hepatocyte cell lines in a PDK-1-dependent manner and can induce HIF1α in different cell types to promote tumor progression in cancer cells." (PMID 31555281, 2019). "In addition, H19 significantly promoted the secondary limited dilution tumor transplantation, whereas PDK1 depletion substantially reversed tumorigenic ability." (PMID 29106390, 2018). "Importantly, in vivo administration of cysteamine strongly reduced tumor size with partial (Glut1, Pdk1, and Hk2) modification of their hypoxic transcriptional signature but without affecting their differentiation status." (PMID 30456364, 2018).
tumor (continued). "Furthermore, H19 and PDK1 levels also displayed a significant correlation in patient tumor samples (n=15)." (PMID 29106390, 2018). "To further explore whether PDK1 acts as a crucial regulator of BCSC maintenance by modulating glycolysis, we evaluated PDK1-positive cancer cell characteristics using a mouse xenograft tumor model." (PMID 29106390, 2018). "Finally, to confirm and complete the signaling pathway for tumor incidence, we examined the mRNA expression of Pdk1 and Akt1 after DMBA administration." (PMID 30126855, 2018). "The result showed that the tumor treated by TMZ combined with SOX9 shRNA or PDK1 inhibitor grew much slower that TMZ single, indicating that SOX9 shRNA and PDK1 inhibitor could significant enhance the suppressing effect of TMZ on nude mice tumor growth." (PMID 29416606, 2018). "For the first time, we illustrated the link between MDK and PDK1/AKT pathway in tumor angiogenesis." (PMID 30001734, 2018). "However, when PDK1 was knocked down or Chibby was overexpressed, β-catenin-enhanced tumor growth was obviously restrained." (PMID 29764469, 2018). "Du and coworkers revealed that mammary-specific ablation of PDK1 could delay tumor initiation, progression, and metastasis in a spontaneous mouse tumor model." (PMID 28430130, 2017). "In addition, we compared the expression of PDK1 in the RB tumor and the adjacent normal appearing uninvolved retina and found significantly lesser expression of PDK1 in normal retina than RB tissue." (PMID 28505181, 2017). "Therefore, the high expression of PDK1 in tumor specimens classified as hypoxic is compatible with the aggressiveness displayed by these tumors." (PMID 29117193, 2017). "In conclusion, our results suggest PDK1 is overexpressed in RB and tumor growth could be attenuated by DCA treatment via inhibition of PI3K/Akt pathway and decrease in PDK1 protein levels." (PMID 28505181, 2017). "The data support the notion that inhibition of PDK1 is not sufficient to prevent tumor formation and progression resulting from loss of PTEN." (PMID 28402933, 2017). "Further, we estimated ROS levels in tumor cells after 48 hours of PDK1 inhibition." (PMID 28505181, 2017). "PDK1 regulates the activity of downstream protein PKCα, a key regulator of cell growth and differentiation in mammalian cells and activation of PKCα is believed to promote tumor progression." (PMID 27494022, 2016). "This biphasic inhibitory effect of PDK1 and RNF126 may indicate that growth and survival of tumor cells are highly sensitive to fine-tuning of the PDK1-mediated metabolic pathway." (PMID 27462466, 2016). "HIF-1α enables tumor cells to harness their energy by resorting to glycolytic instead of oxidative metabolism through up-regulating glucose transporters and pyruvate dehydrogenase kinase 1 (PDK1)." (PMID 26988232, 2016). "Most researchers adopted tumortransplantation mouse model to study PDK1 expression on tumor growth." (PMID 26593251, 2016). "We believed that PDK1 may be one such target and that tumor metabolism was one of these vital processes." (PMID 26593251, 2016). "Indeed, hypomorphic mutation of PDK1 in Pten +/− mice delays the onset of tumorigenesis, and small molecule inhibitors of PDK1 inhibit tumor xenografts and lung colonization." (PMID 26684827, 2015). "Furthermore, more investigative efforts are needed to answer certain unresolved questions by determining the expression of COL11A1 and Akt-PDK1 in clinical tumour specimens from our cohorts." (PMID 26087191, 2015). "Overexpression of PDK1 has been reported to correlate with tumor progression." (PMID 23867003, 2013). "However, PDK-1 staining significantly correlated with tumor invasion (p=0.020), the presence of a positive metastatic lymph node (p=0.040) and larger tumor size (p=0.006)." (PMID 23135628, 2013). "Importantly, varying levels of endogenous Ub-PDK1 were observed in a variety of cell lines derived from different tumor types." (PMID 22347420, 2012).
tumor (continued). "The tumor promoting effects of PPARδ may be related in part to activation of PDK1, which is a PPARδ target gene in keratinocytes." (PMID 21297860, 2011). "This tumor suppressor gene controls PI3K by preventing the activation of PDK-1 and Akt." (PMID 21108789, 2010). "The possibility of blocking PDK1 and mTOR simultaneously in these tumours is likely to be very effective therefore, because of its dual inhibitory activity towards both enzymes, it would be interesting to investigate the effect of 2-O-Bn-InsP5 in these cellular contexts." (PMID 20051961, 2010). "Nevertheless, we verified in the in vivo model that tumor cells were growing in a hypoxic environment by measuring the mRNA levels of well-known HIF-dependent genes such as PDK1 or VEGF, which are controlled by a hypoxia response element (HRE) in their promoters, as well as the HIF-1α expression." (PMID 19956670, 2009). "Recently, it has been demonstrated that reducing the expression of PKB in PTEN-deficient cells reduces aggressive growth and promotes apoptosis, whereas reducing the expression of PDK1 in heterozygous PTEN+/− mice markedly protects these animals from developing a wide range of tumours." (PMID 18349831, 2008). "A high proportion of HNSCC tumours expressed high levels of both PDK-1 and PDH." (PMID 18542064, 2008). "The striking and adverse outcome of those tumours with highest PDK-1 expression could be related to a survival benefit on the cancer cells in vivo, perhaps indicating that marginal hypoxic/anoxic cells are important for tumour growth." (PMID 18542064, 2008). "Additionally, in 4T1 tumors, the immunohistochemical staining for LDH-A and PDK-1 showed marked expression within the whole tumor section, which correlated also with the stronger tumor acidosis observed with CEST pH imaging, whereas 67NR tumors presented less protein quantification for both markers." (PMID 40551171, 2025). "Moreover, in future work, we intend to apply BX-795 and capivasertib to organoid or PDX models to further corroborate the conclusion that EMC2 sensitizes tumor cells to PDK1/AKT inhibition therapy, serving as a complement to existing in vivo and in vitro drug sensitivity experiments." (PMID 40303285, 2025). "Inhibition of Wnt signaling, by targeting PDK1 with Peroxisome proliferator-activated receptor gamma coactivator 1-alpha (PGC1α) or Chibby (a β-catenin antagonist) has been shown to reduce glycolytic activity, leading to impaired tumor growth and altered metabolic dependencies." (PMID 40917745, 2025). "Additionally, PDK1 accelerates tumor growth and metastasis by modulating BGN expression." (PMID 39578715, 2024). "Targeting PDK1 may offer a novel therapeutic strategy for normalizing abnormal tumor metabolism." (PMID 38577616, 2024). "Finally, these data also support that PDK1 partially mediates MAPK4 tumor-promoting activity." (PMID 37531320, 2023). "Notably, HIF-1 α can up-regulate PDK1 and promote glycolysis in tumour cells." (PMID 36452079, 2022). "Next, to reveal the in vivo functions of PDK1-S549 phosphorylation in tumor growth, we employed a xenograft mouse model, and observed that expression of PDK1-S549A could apparently facilitate DLD1-PDK1−/− cell tumor growth compared with PDK1 WT or S549D expressing DLD1-PDK1−/− cells." (PMID 35318320, 2022). "Tumor sizes were measured starting initially after 10 days, and the results showed that miR-148a overexpression significantly inhibited tumor growth, and this effect could be reversed by PDK1 overexpression." (PMID 35892859, 2022). "Speculatively, the primary effect of PDK1 silencing on angiogenesis leads to a secondary effect of increased necrosis, which then triggers, as a tertiary effect, a complex tumor microenvironment response which substantially differs from the straight effects of PDK1 silencing detected in vitro." (PMID 33562444, 2021).
tumor (continued). "The inhibition of HIF-1α by exposure of tumor cells to MJ could induce mitochondrial passage of pyruvate, leading to activation of oxidative phosphorylation and ROS production with concomitant inhibition of GLUT-1, HK 2, LDH A, and PDK-1 axis, a lifeline of tumor metabolism." (PMID 33718176, 2021). "In addition, PDK1 expression itself is augmented in many tumours." (PMID 34879056, 2021). "Analysis of ctDNA or tumor mRNA from patients enrolled in the PALOMA-3, NeoPalAna and MONALEESA-3 trials have identified Rb mutations, activating mutations in PIK3CA and ESR1, increased cyclin E1 and activation of the PDK1-AKT axis as some of the drivers of resistance." (PMID 32344635, 2020). "The fact that tumor-associated PDHE1 subunit phosphorylation was unaffected by diet was consistent with this notion of direct enzymatic inhibition rather than the more indirect inhibition resulting from changes in stimulatory PDP2 phosphatase and inhibitory PDK1 kinase." (PMID 31242205, 2019). "Moreover, emerging evidence is pointing towards a role of PDK1 in the tumour microenvironment." (PMID 29064423, 2017). "Therefore, we inferred that PDK1 is important for tumor cell survival." (PMID 26593251, 2016). "Thus, PDK1 functions as a tumor promoter in human GBC by upregulating JunB." (PMID 26318166, 2015). "Moreover, reducing PDK1 expression in PTEN +/− mice protects these animals from developing a wide range of tumors, thereby providing genetic evidence that PDK1 is a key effector in mediating neoplasia that result from loss of PTEN." (PMID 26684827, 2015). "In this review, we summarize how key glycolytic regulators, including GLUT1, HK2, PFKFB3, PDK1, and LDHA, are controlled by oncogenic, microenvironmental, and non-coding RNA-mediated pathways to reshape tumor metabolism." (PMID 42317327, 2026). "Immunohistochemical analysis of tumor tissues revealed that Liensinine treatment led to a marked reduction in the expression levels of HK2, PDK1, and HIF-1α, while increasing the expression of IDH3B, UQCRC1, and phosphorylated AMPK (P-AMPK)." (PMID 40665352, 2025). "High IGF1R expression enhances the phosphorylation of PDK1 and AKT, activating the PI3K/AKT signaling pathway, thereby promoting cell proliferation and chemotherapy resistance, exacerbating tumor malignancy." (PMID 40290443, 2025). "Our observation demonstrates that tumours likely coopt JAK/STAT activation and Pdk1 elevation to support protein translation and thus tumour proliferation." (PMID 41353199, 2025). "In this study, A04, a compound targeting the degradation of metabolic enzyme PDK1, was developed by PROTAC technology, which significantly inhibited tumor proliferation by disrupting the Warburg effect in cancer cells." (PMID 40873633, 2025). "Pyruvate dehydrogenase kinase 1 (PDK1), a key enzyme in the Warburg Effect, is highly expressed in cancer cells and plays a pivotal role in reprogramming tumor metabolism between glycolysis and OXPHOS." (PMID 40873633, 2025). "Among these, PDK1 mRNA expression was highest in MG-63, followed by 143B, Hu09, HOS, SJSA1, and Saos-2, suggesting a weak correlation between tumor aggressiveness and PDK1 expression in OSCs." (PMID 40730548, 2025). "While most of the mice in the PDK1 and PDP1 groups either died or had easily detectable tumors by day 16, mice in the EV group controlled the tumor better." (PMID 40857407, 2025). "Given that tumor cells heavily depend on glucose and glutamine metabolism, it can be reasonably concluded that SYK activation and PDK1 dimerization-mediated AKT activation occur commonly under conditions of both glucose and glutamine deprivation." (PMID 40774947, 2025). "This activation promotes tumor cell proliferation, adhesion, invasion, and metastasis by engaging pathways such as Ras/Raf/ MEK/ERK and PI3K/PDK1/Akt." (PMID 40559953, 2025). "Akt activation by PDK-1 is crucial for effector-like memory CD8+ T-cell development and tumor immune surveillance." (PMID 40139836, 2025).